EFNA5 (ephrin A5)
Diseases named in the same sentence as EFNA5 in open-access papers (continued):
Sharing a sentence is not in itself a finding about the gene and the disease.
pancreatic cancer (5 papers, 2021 to 2025). "Loss of EFNA5, which had an oncogenic effect, inhibited the development and progression of pancreatic cancer." (PMID 34439315, 2021). "Elevated levels of EFNA5 markedly enhance the growth of pancreatic cancer cells, whereas reducing its expression leads to diminished cell growth." (PMID 39717847, 2024). "Conversely, the downregulation of piR-017061 was shown to upregulate EFNA5, an oncogene in pancreatic cancer progression." (PMID 39717847, 2024). "PiR-017061 arrests pancreatic cancer growth by down-regulating EFNA5 expression." (PMID 40606680, 2025). "Interestingly, a paradoxical function of PIWIL1/HIWI has surfaced, where the upregulation of piR-017061, which binds with PIWIL1, inhibited the mRNA translation of Ephrin A5 (EFNA5), involved in regulating cell growth and proliferation in pancreatic cancer." (PMID 39717847, 2024). "Furthermore, EFNA5 promotes the malignant progression of pancreatic cancer but played a tumor suppressor role in glioma by inhibiting EGFR, tumor invasiveness, and metastasis in hepatoma and colorectal cancer." (PMID 35945523, 2022). "Therefore, targeting PIWI/piRNA-mediated EFNA5 gene regulation could be a new strategy for the treatment of pancreatic cancer." (PMID 34439315, 2021). "EFNA5, as a target of PIWI (P element-induced wimpy testis) integrating RNA (piRNA) piR-017061, is regulated by PIWIL1 to facilitate pancreatic cancer progression." (PMID 37333453, 2023).
colorectal cancer (4 papers, 2020 to 2023). A primary or metastatic malignant neoplasm that affects the colon or rectum. "In recent years, it has been reported that Mir-645 promotes tumor growth, metastasis, invasion and other malignant biological behaviors in colorectal cancer by targeting EFNA5." (PMID 35309935, 2022). "For example, EFNA5 is targeted by miR-645 to promote cell proliferation in colorectal cancer." (PMID 37333453, 2023).
gastric cancer (4 papers, 2020 to 2022). A primary or metastatic malignant neoplasm involving the stomach. "Simultaneously, TGFB2, VEGFB, COL10A1, ERG1 and EFNA5 composed risk model is a promising tool for assessment of gastric cancer survival." (PMID 34332586, 2021). "EFNA5 plays a role in the prognostic effects of chemotherapy in patients with advanced gastric cancer." (PMID 35309935, 2022). "Furthermore, the high expression of EFNA3 and EFNA4 indicates that it is beneficial for OS and DFS of gastric cancer, while the high expression of EFNA5 indicates a low survival rate." (PMID 35309935, 2022). "Finally, we established risk model based on key pathways ligands TGFB2, VEGFB, COL10A1, AREG and EFNA5 to predict gastric cancer survival." (PMID 34332586, 2021).
glioma (4 papers, 2020 to 2025). A benign or malignant brain and spinal cord tumor that arises from glial cells (astrocytes, oligodendrocytes, ependymal cells). "Of note, the expression of ephrinA5 has been found dramatically downregulated in primary gliomas, and the forced expression of EFNA5 (encoding for ephrinA5) diminishes the tumorigenicity of human glioma cells." (PMID 37880732, 2023). "Conversely, ephrin-A1 and ephrin-A5 exhibit tumor-suppressive properties by promoting receptor internalization and degradation, thereby inhibiting glioma cell proliferation and migration." (PMID 41200151, 2025). "Ephrin-A5 is significantly downregulated in primary gliomas." (PMID 41200151, 2025). "Hypermethylation at CpG islands of promoter regions of many ephrins, including EfnA5, and Eph receptors have been demonstrated in acute lymphoblastic leukaemia and miRNAs, such as miR-210 and miR-26b, have been shown to downregulate the expression of EfnA1 in hepatic ischaemia and EphA2 in gliomas." (PMID 31988455, 2020).
medulloblastoma (4 papers, 2015 to 2025). A malignant, invasive embryonal neoplasm arising from the cerebellum. "In the present study, we investigated the effects of genetic loss of ephrin-A5, EphA4, and EphA7 on the spatiotemporal development of medulloblastoma tumors in the context of the smoothened transgenic mouse model system." (PMID 26345456, 2015). "The present study is the first to examine the impact of loss of ephrin-A5 on tumor size in medulloblastoma in vivo." (PMID 26345456, 2015). "In the present study, we sought to determine the effects of loss of ephrin-A5 and the EphA4/EphA7 receptor pair on medulloblastoma tumor growth in vivo." (PMID 26345456, 2015). "Larger tumors in wild-type mice showed increased p-Akt and PCNA, implicating ephrin-A5 as a promoter of medulloblastoma growth via Akt pathway activation." (PMID 41200151, 2025). "The external granule cell layer, which acts as medulloblastoma precursor, shows overexpression of ephrin-A5." (PMID 29682554, 2018). "A noteworthy study also demonstrates a relationship between ephrin-A5 and medulloblastoma by using a mouse model." (PMID 29682554, 2018). "The role of ephrin-A5 in cancerous and normal neural development makes it a likely contributor to the growth and development of medulloblastoma as well." (PMID 26345456, 2015). "Through MRI and tumor dissection, we examined a correlation between ephrin-A5 expression and medulloblastoma tumor size." (PMID 26345456, 2015). "Additionally, our findings suggest possible future therapeutic target for ephrin-A5 in medulloblastoma." (PMID 26345456, 2015). "Further studies are needed to explore the role ephrin-A5 might play in tumorigenesis of medulloblastoma." (PMID 26345456, 2015). "However, ephrin-A5 is a promiscuous ligand that binds to multiple other Eph A and B receptors including EphB1 and EphB2, both of which are present in medulloblastoma tumors." (PMID 26345456, 2015). "Furthermore, since a constitutively active form of Smoothened mimics concentration-dependent actions of SHH, it would be of clinical interest to examine whether dual targeted inhibition of the SHH and ephrin-A5 impact medulloblastoma development." (PMID 26345456, 2015). "In the developing cerebellum, we have previously shown that ephrin-A5 expressed in the external granule cell layers (EGL), which are medulloblastoma precursors." (PMID 26345456, 2015).
schizophrenia (3 papers, 2022 to 2023). A major psychotic disorder characterized by abnormalities in the perception or expression of reality. "In a recent study investigating the molecular organization of human dorsolateral prefrontal cortex, two schizophrenia risk genes, membrane-bound ligand ephrin A5 (EFNA5) and ephrin type-A receptor 5 (EPHA5), were identified to colocalize via cell-cell communication analysis." (PMID 36993732, 2023).
amyotrophic lateral sclerosis (2 papers, 2017 to 2019). Amyotrophic lateral sclerosis (ALS) is a neurodegenerative disease characterized by progressive muscular paralysis reflecting degeneration of motor neurons in the primary motor cortex, corticospinal tracts, brainstem and spinal cord. "In Amyotrophic Lateral Sclerosis (ALS), expression of GPI-anchored Ephrin A5 and uPAR are both significantly altered." (PMID 28103900, 2017).
Autoimmunity (2 papers, 2020 to 2025). The occurrence of an immune reaction against the organism's own cells or tissues.
colon cancer (2 papers, 2012 to 2017). "Similar to our results, the Ephrin-A5 gene (EFNA5) was also reported before as a downregulated gene in colon cancer." (PMID 23049694, 2012).
epilepsy (2 papers, 2021). A brain disorder characterized by episodes of abnormally increased neuronal discharge resulting in transient episodes of sensory or motor neurological dysfunction, or psychic dysfunction. "In addition, we found that miR-484 upregulation is accompanied by the epilepsy progression via inhibition of the three hub gene expression (CTD-3193O13.9, EFNA5, and PRKCB)." (PMID 34722763, 2021).
hepatocellular carcinoma (2 papers, 2021 to 2022). A malignant tumor that arises from hepatocytes. "All of the EPH/ephrins investigated in Hepatocellular Carcinoma (HCC), with the only exception of ephrin-A5, seem to have a negative impact on carcinogenesis and patients’ clinical outcomes." (PMID 34445116, 2021).
hippocampal atrophy (2 papers, 2009 to 2025). "Elucidating the roles of PRUNE2, MAGI2, ARSB and EFNA5 in the regulation of neurodevelopment, protein degradation, apoptosis and neuronal loss could enhance our understanding of hippocampal atrophy and AD." (PMID 19668339, 2009).
lung carcinoma (2 papers, 2020 to 2025). "This feedback loop further augmented the expression of downstream AP-1 target genes, including EFNA5 and PERP, thereby driving lung cancer progression." (PMID 41019373, 2025).
nuclear cataract (2 papers, 2011 to 2021). A cataract (disease) that involves the lens nucleus. "Since mild nuclear cataracts are often present in EphA2–/– lenses, we evaluated the localization of Cx46, Cx50, and Aqp0 by performing immunostaining in 6-week-old control, ephrin-A5–/– and EphA2–/– lens frozen sections." (PMID 34899394, 2021).
Obesity (2 papers, 2023 to 2025). Accumulation of substantial excess body fat. "FTO is a known key gene associated with obesity in humans through the GWAS study and fat deposition on various animals, including pigs and cattle, whereas EFNA5 and RFTN1 are associated with meat color." (PMID 40520431, 2025). "Recent studies have found that the EFNA5 gene can participate in fat thermogenesis and also regulate lipid metabolism, which may be a future therapeutic target for obesity and is also related to the meat quality traits of economic animals." (PMID 36952432, 2023).
osteosarcoma (2 papers, 2020 to 2021). A usually aggressive malignant bone-forming mesenchymal neoplasm, predominantly affecting adolescents and young adults. "EFNA5 was implicated in repairing the DNA damage induced by ionizing radiation, and FBXL17 is involved in U2OS osteosarcoma cellular sensitivity to ionizing radiation." (PMID 34838041, 2021).
type 2 diabetes (2 papers, 2022 to 2023). "Increased EFNA5 expression in islets from human donors with type 2 diabetes." (PMID 35167496, 2022).
Blindness (1 paper, 2015). Blindness is the condition of lacking visual perception defined as a profound reduction in visual perception. "In that study, we found that within 10 days of blindness, the intraneocortical connections of mouse primary visual cortex were altered in a location that was co-registered with an ectopic pattern of ephrin A5 expression." (PMID 26452243, 2015). "Rapid effects of bilateral enucleation on dLGN A high impact result from our study is the very rapid change in the size of dorsal LGN, its reduced gene expression as well as the reduced ephrin A5 expression in cortex as early as 24 hours post-blindness." (PMID 26452243, 2015). "Our initial study demonstrated that by P10, cortical ephrin A5 expression and somatosensory INCs were altered, leading us to conclude that the alteration of sensory INCs in our blindness model occurs between P5 and P10, after a change in gene expression." (PMID 26452243, 2015).
cardiac hypertrophy (1 paper, 2022). "Moreover, transcriptome unbiased analysis of post-MI cardiomyocytes with GRK5 overexpression showed altered levels of several genes previously indicated to be involved in cardiac hypertrophy, remodeling or HF such as Kcne1, Efna5, Psmd8 and several regulators of the extracellular matrix." (PMID 33560342, 2022).
chondrosarcoma (1 paper, 2022). A malignant cartilaginous matrix-producing mesenchymal neoplasm arising from the bone and soft tissue. "Results from their in vitro analysis showed a significant downregulation of ephrin-A5 at the transcriptional level in chondrosarcoma cells compared to normal ones." (PMID 35563562, 2022). "Importantly, a tumor-suppressive effect was noticed by ephrin-A5 in chondrosarcoma due to an exclusive inhibitory effect against carcinogenesis and tumor progression." (PMID 35563562, 2022). "Therefore, ephrin-A5 is not implicated in cell–cell adhesion interactions that could remodel the microenvironment to promote the expansion of chondrosarcoma." (PMID 35563562, 2022).
congenital cataracts (1 paper, 2023). "A role for Ephrin signaling in eye development is also emerging: dominant mutations in EPHA2 cause isolated congenital cataracts, and its ligand EFNA5 is important for normal lens development." (PMID 36830662, 2023).
dry eye (1 paper, 2010). "This is in agreement with previous studies in symptomatic, moderate dry eye patients, where there were no increases in levels of IL-1β, IL-6, IL-8/CXCL8, GRO-b, ICAM-1, TRAIL, or ephrin A5 in tear fluid." (PMID 20508732, 2010).
heart failure (1 paper, 2021). Inability of the heart to pump blood at an adequate rate to meet tissue metabolic requirements. "It is, however, noteworthy that EFNA4, EFNA5 as well as TNFRSF1α were among the upregulated proteins of a correlation network uniquely associated with the regulation of actin filament process, ephrin receptor signaling, and regulation of muscle system processes in a heart failure study." (PMID 33572894, 2021).
insomnia (1 paper, 2024). A sleep disorder characterized by difficulty in falling asleep and/or remaining asleep. "In the realm of sleep and circadian health, reported genetic associations corroborated the relevance of EFNA5, ZNF521, WWOX, ALG10B, PAM and SDK1 with insomnia, daytime napping, or chronotype traits." (PMID 39070651, 2024).
ischemic stroke (1 paper, 2023). A stroke disorder caused by obstruction of blood flow to the brain, due to thrombotic (local blood clot formation) or embolic (due to a blood clot or other material traveling from another site) event. "Similarly, Ephrin A5, a development-associated growth inhibitor, is upregulated in astrocytes after ischemic stroke, and local inhibition of Ephrin A5 signaling in the sub-acute phase promotes axonal growth and functional recovery." (PMID 39086680, 2023).
lung adenocarcinoma (1 paper, 2022). A carcinoma that arises from the lung and is characterized by the presence of malignant glandular epithelial cells. "Univariate and multivariate analyses showed that pathological stage and EFNA5 expression were independent prognostic factors of resected lung adenocarcinoma, correlating with the TCGA database results." (PMID 35945523, 2022). "In summary, EFNAs are crucial in tumor immune regulation, and EFNA5 is a prognostic marker in lung adenocarcinoma." (PMID 35945523, 2022). "RT-qPCR, western blot and immunohistochemistry (IHC) were used to validate the expression level and significant clinical value of EFNA5 in lung adenocarcinoma cell lines and tissues." (PMID 35945523, 2022). "Eventually, EFNA5 was an independent prognostic factor in lung adenocarcinoma." (PMID 35945523, 2022). "IHC was used to validate EFNA5 as a critical prognostic factor in lung adenocarcinoma." (PMID 35945523, 2022).
microphthalmia (1 paper, 2025). Congenital or developmental anomaly in which the eyeballs are abnormally small. "While we did not include ephrin-A5-/- mice with microphthalmia in this study, we observed ephrin-A5-/- mice with smaller lens volumes also had smaller eye volumes (data not shown)." (PMID 41245154, 2025).
Ovarian cyst (1 paper, 2006). The presence of one or more cysts of the ovary. "Hence EphA1, EphA2, EphB2, EphB3, EphB6, ephrin A1, ephrin A5 and ephrin B1 were selected for further analysis in an additional fourteen tumor samples, one ovarian cyst and one ovarian adenoma." (PMID 16737551, 2006).
Parkinson disease (1 paper, 2009). A progressive degenerative disorder of the central nervous system characterized by loss of dopamine producing neurons in the substantia nigra and the presence of Lewy bodies in the substantia nigra and locus coeruleus. "EFNA5 and its interactions with other axon guidance genes have been linked to susceptibility to developing Parkinson's disease." (PMID 19668339, 2009). "It is possible that the EFNA5 findings are consistent with a neurodevelopmental process in both AD and Parkinson's disease." (PMID 19668339, 2009).
rhabdomyosarcoma (1 paper, 2022). A rare aggressive malignant mesenchymal neoplasm arising from skeletal muscle. "It has been observed that enhanced interaction between EPHA3 and its ligand ephrin-A5/Fc in rhabdomyosarcoma modulates Rho GTPases, leading to a decrease in cell–fibronectin adhesion and migration toward stromal cell-derived factor 1 (SDF-1)." (PMID 35563562, 2022).
rhinitis (1 paper, 2023). An inflammation of the mucous membrane lining the nose, usually associated with nasal discharge. "For example, Ly6G+ SiglecF+ neutrophils expressing “neurosupportive” genes (Efna5 and Mtap1b) accumulate in the olfactory neuroepithelium during recovery from intranasal methimazole-induced rhinitis, coinciding with active neurogenesis." (PMID 37961609, 2023).
serous carcinoma (1 paper, 2025). "High-grade serous carcinoma tends to overexpress EFNA5, especially at aggressive stages." (PMID 40567611, 2025).
serous ovarian cancer (1 paper, 2023). "EFNA5 is an unfavorable factor in high-grade serous ovarian cancer because it is a non-canonical Eph-receptor ligand." (PMID 37337170, 2023).
severe combined immunodeficiency (1 paper, 2021). Severe combined immunodeficiency (SCID) comprises a group of rare monogenic primary immunodeficiency disorders characterized by a lack of functional peripheral T lymphocytes resulting in early-onset severe respiratory infections and failure to thrive. "EFNA5 has been associated with severe combined immunodeficiency with sensitivity to ionizing radiation (SCID) disease." (PMID 34838041, 2021). "Using GeneCards and MalaCards, showed EFNA5, FBXL17, and FER have been associated with severe combined immunodeficiency characterized by sensitivity to ionizing radiation disease, DNA damage response after ionizing radiation and activation of the ataxia-telangiectasia mutated protein, respectively." (PMID 34838041, 2021).
temporal lobe epilepsy (1 paper, 2020). A localization-related (focal) form of epilepsy characterized by recurrent seizures that arise from foci within the temporal lobe, most commonly from its mesial aspect. "For example, inhibition of Efna5 could downregulate ERK1/2 phosphorylation, which is accompanied by depression neurogenesis and angiogenesis in the hippocampal formation of temporal lobe epilepsy (TLE)." (PMID 33102589, 2020).